CXCR4 (C-X-C motif chemokine receptor 4)
Diseases named in the same sentence as CXCR4 in open-access papers (continued):
Sharing a sentence is not in itself a finding about the gene and the disease.
Autoimmunity (15 papers, 2011 to 2025). The occurrence of an immune reaction against the organism's own cells or tissues. "Ablation of either of the components of the SDF-1/CXCR4 axis generates a similar phenotype of deficient B lymphopoiesis and myelopoiesis, disturbed immune responses leading to cancers, autoimmunity and inflammatory diseases." (PMID 30622535, 2018). "CXCR4, as a surrogate marker for autoimmunity, has been implicated in kidney homeostasis and regeneration and is significantly increased in kidney tumor and human kidney biopsies from patients with proteinuria kidney diseases." (PMID 29849929, 2018). "In conclusion, we have identified novel anti-GPCR abs against the chemokine receptors CXCR3 and CXCR4 in patients with systemic sclerosis linking autoimmunity with interstitial lung disease." (PMID 29566745, 2018). "SDF-1/CXCR4 axis is essential in directing BD-MSCs to migrate toward inflammatory sites to control autoimmunity." (PMID 28348600, 2017). "In this study, we focused on the CXC α-chemokine Stromal cell Derived Factor-1 (SDF-1)/CXCL12, which together with its main receptor CXCR4, constitutes the chemokine/receptor axis attracting the greatest level of interest in autoimmunity." (PMID 23244336, 2012). "In autoimmunity there are indications that the interaction of CXCR4 and CXCL12 could be important." (PMID 27519689, 2016).
metastasis (15 papers, 2008 to 2025). The spread or migration of cancer cells from one part of the body (where they first appeared) to another. "For example, CLDN2 expression was recently linked to increased incidence of CRC-associated liver metastasis, whereas CXCR4 and CYP24A1 are increasingly recognized as prognostic markers for CRC progression." (PMID 35159043, 2022). "Upregulation of CXCR4 is accepted to be indicative of shorter overall survival and related to an elevated risk of developing lymph node and liver metastasis via the interaction with CXCL12, which can further promote angiogenesis and the formation of new blood and lymphatic vessels." (PMID 35163198, 2022). "CXCR4 expression was correlated with high-grade nitrotyrosine staining (p < 0.001) and lymph node metastasis (p = 0.0116)." (PMID 18826577, 2008). "Nuclear CXCR4 was initially observed in diverse tumor tissues and correlated with significant predictors for poor overall malignant survival, lymphovascular invasion and lymph node metastasis." (PMID 23468933, 2013). "Kaplan-Meier survival curves demonstrated that high CXCR4 expression, solid ASC and lymph node metastasis indicated decreased DFS and OS." (PMID 31949484, 2020). "Compared with the group without lymph node or liver metastasis, the proportion of CXCR4 high expression in the group with metastasis was slightly higher, but there was no statistical significance." (PMID 38524630, 2024).
acute kidney injury (14 papers, 2012 to 2025). Sudden and sustained deterioration of the kidney function characterized by decreased glomerular filtration rate, increased serum creatinine or oliguria. "Preconditioning with insulin-like growth factor-(IGF-) 1 improved the migration capacity of MSCs and restored normal renal function after acute kidney injury through a mechanism involving the upregulation of CXCR4." (PMID 24381939, 2013). "For instance, studies in acute kidney injury support a reno-protective function for SDF-1/CXCR4, whereas CXCR4-mediated hyperproliferation may actually contribute to the development of certain glomerular diseases." (PMID 24637920, 2014). "Moreover, in acute kidney injury (AKI), FGF23 has turned out to stimulate cell proliferation promoting regeneration of injured tubules through influencing SDF-1/CXCR4 signaling." (PMID 35011602, 2021). "In an acute kidney injury mouse model, overexpression of CXCR4 in BM-MSCs did not result in an increase of BM-MSCs in the injured kidney and blockage of CXCR4 did not affect the intramyocardial migration of murine BM-MSCs to ischemic areas in mice." (PMID 28330488, 2017). "This is in contrast to a report showing that the overexpression of CXCR4 did not improve MSC homing in a mouse model of cisplatin-induced acute kidney injury." (PMID 24381939, 2013). "Other studies have shown that CXCR4 overexpression of mesenchymal stem cells does not improve the homing and therapeutic potential of these cells in acute kidney injury, suggesting that the type and severity of kidney injury may influence the homing of modified stem cells." (PMID 40984643, 2025). "Nonetheless, genetic modification of MSCs to overexpress CXCR4 and CXCR7 did not increase their homing therapeutic capacities in acute kidney injury in vivo models." (PMID 37287066, 2023). "On the contrary, others have shown that lentiviral overexpression of CXCR4 and CXCR7 in murine MSC did not improve the homing and therapeutic potential of these cells in experimental acute kidney injury." (PMID 24757448, 2014).
influenza (14 papers, 2013 to 2025). An acute viral infection of the respiratory tract, occurring in isolated cases, in epidemics, or in pandemics; it is caused by serologically different strains of viruses (influenzaviruses) designated A, B, and C, has a 3-day incubation period, and usually lasts for 3 to 10 days. "CXCR4-deficient or control GC B cells were compared to WT CD45.1+ cells from the same medLNs 23–25 days after influenza infection." (PMID 24184055, 2013). "Recent studies have further demonstrated that Cxcr4 is upregulated following influenza infection, modulating neutrophil phagocytic activity, ligand-specific migration, and the induction of neutrophil extracellular traps." (PMID 40612507, 2025). "The expression of CXCR4 was also higher on circulating TFH-like cells from older people 7 d after seasonal influenza vaccination compared with younger individuals, with CXCR5 expression being consistent between the age groups." (PMID 37217705, 2023). "Testing our method on 238D2, an antagonistic anti-CXCR4 nanobody, we were able to find new nanobodies against CXCR4 and to identify influenza hemagglutinin as an off-target of 238D2." (PMID 36077163, 2022). "Aged murine neutrophils upregulate CXCR4, which is also involved in neutrophil trafficking into LNs, although one study showed downregulation of CXCR4 in murine dLN neutrophils 12 h following Influenza vaccination." (PMID 34411302, 2021). "The decreasing expression of CXCR4 marker from naive to memory to activated memory B cells was observed in clusters B1 to B3, which was also mentioned in the similar subsets identified from an influenza vaccination study." (PMID 34835283, 2021). "A previous study has shown that CXCR4+CXCR5+ double-positive Tfh cells arise following influenza infection and could be identified within the GC43." (PMID 28303891, 2017). "Furthermore, CXCR4 silencing reverted CB inhibitory effect on pDC activated with Influenza or with X4 or R5 HIV-1." (PMID 28181493, 2017). "In addition, CXCR4-expressing ASCs may traffic to sites of inflammation, such as the influenza-infected lung, in response to local production of inflammatory chemokines." (PMID 25171166, 2014). "To generalize our findings, we verified that CXCR4 silencing also blocked CB inhibitory effect on pDC activated by a CCR5-tropic (R5) HIV-1 and Influenza." (PMID 28181493, 2017). "Lung-recruited neutrophils induced CCR1, CCR2, CCR3, CCR5, CXCR1, CXCR3, CXCR4, which were absent or marginally induced in peripheral blood neutrophils from influenza-infected mice." (PMID 31041196, 2019). "They demonstrated that early recruited neutrophils into influenza-infected trachea deposit long-lasting SDF-1-containing trails, which provide both chemotactic and haptotactic cues for efficient CXCR4 expressing CD8+ T cell migration and effector functions in influenza-infected tissues." (PMID 27038487, 2016). "Therefore, a requirement for CXCR4-expression by GC B cells is not specific to influenza infection or to the medLN." (PMID 24184055, 2013).
invasive breast carcinoma (14 papers, 2012 to 2025). A carcinoma that infiltrates the breast parenchyma. "Collectively, our findings highlight miR-139-mediated suppression of CXCR4/p-Akt signaling and thereby affected mesenchymal stem-cell genesis, indicating its potential as a therapeutic target for invasive breast cancer." (PMID 34070538, 2021). "CXCR4 is a chemokine receptor frequently overexpressed in invasive breast cancer that has been shown to play a major role in signaling pathways involved in metastasis." (PMID 30191351, 2018). "The Pearson's correlation analysis identified the positive correlation of KLF8 and CXCR4 in invasive breast cancers, specifically in invasive ductal carcinoma (IDC) rather than invasive lobular carcinoma (ILC)." (PMID 26993780, 2016). "The invasive breast cancer cell line, MDA-MB-231, was transfected with PEI-GO in complex with siRNAs against CXCR4 (siCXCR4)." (PMID 27173676, 2016). "To do this, we patterned cells to mimic the disorganization of CXCL12+, CXCR4+, and CXCR7+ cells observed in invasive breast cancer." (PMID 25909600, 2015). "We found significant lower expression prevalences in normal tissue and benign breast diseases compared to invasive breast cancer, showing high cancer-specificity of CAIX, GLUT1 and especially CXCR4." (PMID 24206539, 2013). "To test this hypothesis, we first confirmed that the gene expression of CXCR4, LASP1, and eIF4A are upregulated in invasive breast cancer." (PMID 31106142, 2019). "Of the 127 selected articles (CAIX, GLUT1, CXCR4 IGF1R), we excluded ten articles from the analysis due to (suspected) overlap of study populations, and one article because we could not distinguish between carcinoma in situ and invasive breast cancer." (PMID 24206539, 2013).
mantle cell lymphoma (14 papers, 2012 to 2026). Mantle cell lymphoma is a rare form of malignant non-Hodgkin lymphoma affecting B lymphocytes in the lymph nodes in a region called the ``mantle zone''. "Other studies have shown that binding of CXCL12 to CXCR4 in mantle cell lymphoma promotes the migration of the cells and is associated with an invasive disease." (PMID 24859274, 2014). "Also in the present study we observed higher CXCR4 expression in follicular lymphomas, small B-cell lymphomas and mantle cell lymphomas, which have predisposition to spread into the blood." (PMID 24859274, 2014). "More recently, a study reported the application of a CRISPR-Cas9 system to disrupt CXCR4 expression in mantle cell lymphomas (MCL), a highly aggressive subset of B-cell non-Hodgkin lymphomas (NHLs)." (PMID 35154242, 2021). "For CXCR4 expression, studies found that mantle cell lymphomas displayed high levels of CXCR4 expression, which is critical for malignant B cell trafficking and homing to supportive tissue microenvironment." (PMID 32757068, 2020). "Mantle cell lymphomas also express high levels of chemokine receptors CXCR4, CXCR5, and integrin α4β1." (PMID 22567280, 2012). "We discovered an expansion of B1 B cells mediated by CXCR4C1013G, indicating a susceptibility of hyperactivated CXCR4 signaling toward mature B-cell neoplasms, as this fraction of B cells harbor the potential for transformation into CLL and mantle cell lymphoma." (PMID 34363012, 2021). "We think it might be interesting to further investigate the role of [68Ga]pentixafor PET and the feasibility of CXCR4-directed radioligand therapy in mantle cell lymphoma." (PMID 32757068, 2020). "Thus, CXCR4 inhibitors coupled with anti-α4β1 integrin antibodies were shown to abrogate both adhesion and chemoresistance of mantle cell lymphoma." (PMID 22567280, 2012). "Additionally, CXCR4 has recently emerged as an interesting molecular target in marginal zone lymphoma, gastric mucosa-associated lymphoid tissue (MALT) lymphoma, mantle cell lymphoma, myeloproliferative neoplasms as well as primary lymphoma of the central nervous system." (PMID 34885030, 2021). "Overexpression of CXCR4 was detected with [68Ga]pentixafor PET/CT in lymphoplasmacytic lymphoma, marginal zone lymphoma, DLBCL, follicular lymphoma, mantle cell lymphoma, unclassified indolent B cell lymphoma, and EATL." (PMID 32757068, 2020).
marginal zone lymphoma (14 papers, 2017 to 2025). A usually indolent mature B-cell lymphoma, arising from the marginal zone of lymphoid tissues. "Negative CXCR3 in immunohistochemical staining is a unique subtype of marginal zone lymphoma, and there is a significant correlation between the CXCR4 expression level and bone marrow involvement." (PMID 40427609, 2025). "Marginal zone lymphoma (MZL) is characterized by an intense expression of the C-X-C motif chemokine receptor 4 (CXCR4) in sites of disease." (PMID 39090381, 2024). "Moreover, previous work has shown that CXCR4-directed imaging can be used as an accurate staging tool in patients with marginal zone lymphoma." (PMID 37943339, 2024). "C-X-C motif chemokine receptor 4 (CXCR4)-directed molecular imaging provides excellent read-out capabilities in patients with marginal zone lymphoma (MZL)." (PMID 39090381, 2024). "For instance, in specimen of patients afflicted with marginal zone lymphoma (MZL), more than 90% revealed relevant CXCR4 expression and those ex-vivo findings then laid the proper groundwork for in-vivo imaging using CXCR4-directed [68Ga]Ga-PentixaFor PET/CT." (PMID 37286923, 2023). "Moreover, CXCR4-directed imaging has also been applied to 22 treatment-naïve patients affected with marginal zone lymphoma (MZL)." (PMID 35674738, 2022). "Herein, we describe for the first time the proof-of-concept of CXCR4-directed PET MRI with [68Ga]Pentixafor in response assessment in a patient with extranodal marginal zone lymphoma (MZL) of the orbital cavities and compare it to standard [18F]FDG PET imaging." (PMID 28577295, 2017).
papillary thyroid carcinoma (14 papers, 2008 to 2025). "This study aimed to examine HIF-2α, TWIST, and CXCR4 expression in papillary thyroid carcinoma (PTC) and assesses the association of their expression with clinicopathological indicators." (PMID 24288553, 2013). "It has also been reported in the literature that the SDF-1α/CXCR4 axis promotes the migration and invasiveness of human papillary thyroid cancer cells by the NF-κB signaling pathway." (PMID 36159583, 2022). "A CXCR4 antagonist (AMD3100) has also been shown to have significant anti-tumor effects on BHP10-3 papillary thyroid carcinoma cells in vivo and in vitro." (PMID 34790698, 2021). "Nitric oxide induces functional CXCR4 in vitro, and levels of the NO marker nitrotyrosine are correlated with CXCR4 expression and lymph node metastasis in human papillary thyroid carcinoma." (PMID 18826577, 2008). "We considered the possibility that the inflammatory stimulant NO is involved in the expression of CXCR4 in papillary thyroid carcinoma (PTC) because NO has been shown to up-regulate the expression of prometastatic and proangiogenic genes including VEGF, VEGF-C, and VEGF-D." (PMID 18826577, 2008). "NO may induce lymph node metastasis via CXCR4 induction in papillary thyroid carcinoma." (PMID 18826577, 2008). "Nitrite/nitrate levels and functional CXCR4 expression were assessed in K1 and B-CPAP papillary thyroid carcinoma (PTC) cells after induction and/or inhibition of NO synthesis." (PMID 18826577, 2008). "Therefore, the aim of this study was to explore the clinicopathological role of CXCR4 and SDF-1 with respect to the tumor immune microenvironment in differentiated thyroid carcinoma on a protein and RNA level." (PMID 36419107, 2022). "The chemokine axis CXCR4/SDF-1 correlates with more aggressive tumors, but little is known concerning the prognostic relevance in relation to the tumor immune microenvironment of differentiated thyroid cancer (DTC)." (PMID 36419107, 2022). "The authors found a complete absence of CXCR4 expression in papillary thyroid carcinoma, whereas at least focal CXCR4 expression was found in ATC." (PMID 27487122, 2016). "The finding of elevated CXCR4 in the AYA group echoes reports implicating CXCR4 in tumor invasiveness, suggesting it may also be a promising therapeutic target for intervention in papillary thyroid carcinoma." (PMID 41374320, 2025). "However, contrary to our observation, CXCR4 is observed to highly expressed in high-grade serous epithelial OC which positively related to tumor dissemination and metastasis while CCDC80 is down-regulated in papillary thyroid carcinomas and considered as a tumor suppressor role." (PMID 32716025, 2020).